SRGN (serglycin)
Diseases named in the same sentence as SRGN in open-access papers (continued):
Sharing a sentence is not in itself a finding about the gene and the disease.
tumor (continued). "Another possibility is that released serglycin either by tumor cells or platelets may participate in bridging tumor cells with activated platelets or platelet microparticles as well as endothelial cells." (PMID 24455486, 2014). "Serglycin is expressed in all normal hematopoietic cells and hematopoietic tumor cell lines." (PMID 24455486, 2014). "Secreted serglycin in the tumor microenvironment may interact with CD44 on tumor cells triggering CD44 signaling." (PMID 24455486, 2014). "Apart from its direct beneficial role to tumor cells, serglycin may promote the inflammatory process in the tumor cell microenvironment thus enhancing tumor development." (PMID 24455486, 2014). "Collectively, the expression of serglycin seems to benefit tumor cells in multiple ways." (PMID 24455486, 2014). "In vitro, serglycin was highly expressed and secreted by aggressive tumor cell lines." (PMID 24455486, 2014). "Serglycin may be involved in tumor cell metastasis either via its proven role in activation of platelets or directly affecting the binding of tumor cells to platelets." (PMID 24455486, 2014). "Platelet serglycin may influence the release of these factors in the tumor microenvironment, which promote tumor cell growth and metastasis." (PMID 24455486, 2014). "In the present review, we discuss the role of serglycin in inflammation and tumor progression." (PMID 24455486, 2014). "This suggests that high SRGN expression may drive a dysregulated hyperinflammatory state, potentially leading to immune exhaustion or functional impairment of M1 macrophages—shifting their role from antitumor to pro-tumor effect." (PMID 41476965, 2025). "It was reported that SRGN could be transcriptionally regulated in the tumor cells." (PMID 36133820, 2022). "Notably, all the correctly classified FDC-S cases were positive for at least two markers among CXCL13, CD21, CD35, FDCSP and SRGN; this information could be easily applicable in the routine diagnosis of this tumor." (PMID 28145886, 2017). "However the increased E-cadherin levels was not matched with increased transcription of Cdh1 in the SG-/- tumour cells suggesting that serglycin may have a role in E-cadherin degradation during tumour progression." (PMID 27223472, 2016). "In addition, we found small but significantly changed mRNA expression levels of other cadherins indicating that serglycin may be involved in the regulation of protocadherin and cadherin levels in the growing tumour tissue." (PMID 27223472, 2016). "Since we could not detect any tumour cells in the SG-/- lung by immunohistochemistry or by RT-PCR our results suggests that extravasation indeed may be blocked in the serglycin-deficient mice." (PMID 27223472, 2016). "Interestingly, the megakaryocytic tumor cells synthesize a hybrid CS/HS serglycin." (PMID 24455486, 2014). "Our data from this and our previous study demonstrate a role of serglycin secreted by malignant cells as an inhibitor of complement activation in the tumor microenvironment that may protect tumor cells from complement attack in the early phase of disease or later during immunotherapy." (PMID 24205138, 2013). "On the other hand, serglycin (SRGN), a factor within the lung TME secreted by both tumour and stromal cells, promotes NSCLC aggressiveness." (PMID 40407951, 2025). "Compared to HCC patients with low SRGN levels, HCC patients with high SRGN expression had larger neoplasm diameters, accompanied by significant tumor metastasis, and were predominantly in poorer III-IV clinical stages." (PMID 40384866, 2025). "Following this, we performed a more detailed examination regarding the tumor cells and classified four tumor cell subtypes based on the expression levels of marker genes (C0 MUC5AC+ subtype, C1 NDUFAB1+ subtype, C2 SRGN+ subtype, C3 HEPACAM2+ subtype)." (PMID 40688093, 2025).
tumor (continued). "In the postinfusion NK cells, NK1 was the dominant subcluster, expressing high levels of cytotoxic effector genes (CST7, SRGN, and GZMA), indicating its key role in tumor cell killing." (PMID 40315330, 2025). "After two weeks, tumour analysis revealed that WT CAFs significantly promoted CAL27 tumour growth compared with CAL27 alone, but were markedly suppressed by either 3‐MA or SRGN KO." (PMID 41410182, 2025). "Single-cell analysis revealed SRGN expression across 17 distinct cell subpopulations, with notable expression in dendritic cells, endothelial cells, macrophages, fibroblasts, mast cells, plasma cells, monocytes, T cells, and tumor-associated macrophages (TAMs)." (PMID 41476965, 2025). "SRGN and CD206 were upregulated, whereas CD80 was downregulated in subcutaneous tumor tissues in HepG2SG xenograft mice compared with HepG2-NC mice (*p < 0.05, **p < 0.01)." (PMID 41476965, 2025). "There were several transcripts showing elevated expression in GBM stromal cell types versus stromal cell types in the grade III tumor, including IGFBP2 (ECM glycoprotein), ANXA1 (ECM-affiliated), ITGA7 (integrin), and SRGN (proteoglycan)." (PMID 41366031, 2025). "In further exploration, it was found for the first time that SRGN can regulate CRISPLD2 expression through the YAP axis and positively promote tumor cell proliferation." (PMID 40384866, 2025). "Based on the comprehensive analysis and experimental evidence, we concluded that SRGN regulated YAP expression and nuclear localization, impacting tumor cell growth in HCC." (PMID 40384866, 2025). "We subsequently examined the expression of SRGN and CD44 in cell line, and found that SRGN was mainly expressed in tumour cells, whereas CD44 was detected in fibroblasts." (PMID 38862740, 2024). "The number of mast cells in TEM also correlates with tumor grade, and their degranulation within the tumor leads to the release of chemokines and other tumor-promoting compounds such as CXCR4, STAT3 and serglycin which trigger further tumor progression." (PMID 38275375, 2023). "The tumor stains for one or more of the FDC markers including CD21, CD23, CD35, D2-40, clusterin, CXCL13, FDC-secreted protein and Serglycin." (PMID 35941667, 2022). "Silencing of the serglycin gene (SRGN) resulted in less proliferation, colony formation, stemness accompanied by astrocytic differentiation, and diminished tumor cell growth in vivo." (PMID 35494005, 2022). "In conclusion, our findings substantiate that SRGN and its binding partners promote ESCC aggressiveness from multiple aspects, including autocrine activation of intracellular signaling pathway and tumor microenvironment remodeling." (PMID 33456569, 2021). "The analysis revealed a significant positive correlation between SRGN expression and FAK activation in human tumor samples, thus corroborating the link of SRGN to FAK signaling in GCTB." (PMID 34556636, 2021). "qRT-PCR analysis of serglycin, a cell-associated PG which is intracellular, unlike other HSPGs, showed decreased levels, around 35% of the values obtained for healthy tissues, independent of the metastatic nature of the tumor, and affecting 70–75% of the samples analyzed (p < 0.05)." (PMID 29940912, 2018). "Serglycin is the major proteoglycan in MCs and can act as an immune modulator in the TME and enhance the resistance of tumor cells to various therapeutic agents." (PMID 28445977, 2017). "FDC secreted protein (FDCSP) and Serglycin (SRGN) proved to be specific markers of FDC and related tumor." (PMID 28145886, 2017). "Here, we report that serglycin knockdown in NPC cells inhibited cell sphere formation and tumor seeding abilities." (PMID 27809309, 2016). "However, at this time it could not be excluded that simply the metastatic latency was increased in the serglycin-deficient F2 mice (75% C57BL/6 and 25% FVB/n) as tumour onset is delayed at PyMT expression in congenic C57BL/6 mice compared to congenic FVB/n mice." (PMID 27223472, 2016).
tumor (continued). "To investigate the role of serglycin in EMT, we analysed the levels of E-cadherin in SG+/- and SG-/- primary tumours by Western blot and with immunohistochemistry." (PMID 27223472, 2016). "In addition, when 2 × 102 cells were injected into nude mice, 50% of the mice (3/6) formed palpable tumors in the S18 scrambled cells group compared with no mice (0/6) in the S18 SG KD2 group, suggesting that serglycin level was associated with tumorigenesis or tumor-initiating capacity in vivo." (PMID 27809309, 2016). "In addition, when assessing the level of a panel of angiogenic factors on a multiplex antibody array some factors were reduced in the SG-/- tumour tissue, but overall the serglycin-deficient tumour tissue showed no striking differences to the SG+/- tumour tissue." (PMID 27223472, 2016). "Serglycin may regulate the biosynthesis, secretion, and targeted delivery of many inflammatory mediators, which can act in various cell types in paracrine and autocrine manner in multiple ways to enhance inflammatory process and support tumor growth and metastasis." (PMID 24455486, 2014). "Notably, the heterogeneity of EPCs, particularly the identification of four distinct tumor cell subtypes (C0 MUC5AC+, C1 NDUFAB1+, C2 SRGN+, and C3 HEPACAM2+), highlighted the complexity of GC biology." (PMID 40688093, 2025). "To assess CAFs' impact on tumour invasion in vivo, we created orthotopic xenografts using nude mice randomized into four groups: (a) CAL27; (b) CAL27 + WT CAFs; (c) CAL27 + WT CAFs treated with 3‐MA; (d) CAL27 + SRGN‐KO CAFs." (PMID 41410182, 2025). "Moreover, our investigation reveals a significant downregulation in the expression levels of these uEV-associated biomarkers after surgery, indicating the likely secretion of SRGN, FLI1, and MACROH2A2 by tumor cellular EVs." (PMID 39816677, 2025). "Importantly, the addition of rabbit anti-SRGN antibody inhibited KDM5B up-regulation and IL-8 production induced by treatment with the CMs of tumour cells." (PMID 38862740, 2024). "We established that suppression of SRGN in LN-18shSRGN cells substantially down-regulates IL-8/CXCR-2 expression and signaling that is active and important in control LN-18shSCR cells to regulate tumor cell functions." (PMID 38672477, 2024). "Srgn, on the other hand, was upregulated in miR-32 expressing hiMyc tumors, but SRGN downregulated in CRPC compared with PC patient tumor specimens (data not shown)." (PMID 35228520, 2022). "Upregulated SRGN expression and secretion are observed in GCTB tumor cells and patients." (PMID 34556636, 2021). "Upregulation of SRGN in GCTB was likely independent of H3.3G34W mutation, as its high expression in a GCTB tumor without H3.3G34W mutation, GCTB-4, was also observed." (PMID 34556636, 2021). "Moreover, SRGN, S100A11, and FCER1G contribute to the identification of mast cells in tumor microenvironments." (PMID 34575089, 2021). "Serglycin, the only intracellular PG, promoted tumor cell growth through interacting with CD44, and it was found that combining targeting serglycin and CD44 could be an effective therapy." (PMID 32825245, 2020). "In addition, two other transcripts (serglycin and FOXF1 adjacent non-coding developmental regulatory RNA) were identically found to be downregulated in MDR cells of both tumor models (NSCLC and CML)." (PMID 31947507, 2020). "Our study leverages data from plasma RNA and CTCs, published studies and focused data mining, to propose a testable model in which high concentration of PF4 induces platelet attraction into the tumor microenvironment and regulates expression and/or availability of CLU, CCL5, TGFB1, SRGN and SPARC." (PMID 31215484, 2019). "In summary the patterns of alterations in the levels of expression of HSPG core proteins in CRCs is quite similar for ECM molecules, syndecans and serglycin, independent of tumor location, while glypicans display differences between RS- and LS- malignances." (PMID 29940912, 2018).
tumor (continued). "Proteoglycan serglycin (SRGN) proteins are involved in tumor metastasis, but their role in TNBC has not yet been elucidated." (PMID 28692037, 2017). "This is however less likely because circulating tumour cells were detected in blood also in SG-/- mice suggesting that intravasation was not dependent on serglycin." (PMID 27223472, 2016). "This suggests that the major contributors of serglycin in the lesion are not the tumor cells per se, but rather are cells within the tumor stroma." (PMID 25978773, 2015). "We observed a high expression of serglycin in tumor tissue of serglycin wild type mice, while no signal was detected in serglycin knockout mice (undetectable Ct value)." (PMID 25978773, 2015). "We found that lack of serglycin did not affect the penetrance for tumor development, which was 100% in both groups." (PMID 25978773, 2015). "The loss of exon 2 (49 amino acids) has been also demonstrated in human neutrophils; however, alternative splicing of serglycin in tumor cells has not been previously reported." (PMID 26581653, 2015). "The absence of serglycin also enhances the functionality of tumor vessels, which were better perfused than that developed in tumors in serglycin wild type mice." (PMID 26581653, 2015). "The absence of serglycin also enhances the tumor vessel functionality, which is better perfused than in tumors from serglycin wild type mice." (PMID 25978773, 2015). "Although serglycin does not contain a transmembrane domain, this PG was initially discovered at the cell membrane of rat L2 yolk sac tumor cells and was the first PG gene to be cloned." (PMID 24205138, 2013). "A dose-dependent in exogenous recombinant SRGN protein concentrations was positively correlated with enhanced migratory and metastatic capacities of HCC cells, directly demonstrating SRGN's autocrine-driven role in potentiating tumor cell invasiveness and metastatic progression." (PMID 40384866, 2025). "Notably, immunostaining analysis showed that SRGN was mainly expressed in the tumor area of GCTB, but not in para-tumor stroma." (PMID 34556636, 2021). "Moreover, potential crosstalk between serglycin and CD44, may function as an amplifier modulating a variety of tumor induction signals." (PMID 28445977, 2017). "Interestingly, PyMT+ cells were found in the blood of both PyMT+ SG+/- and SG-/- mice, suggesting that tumour intravasation can occur in the absence of serglycin." (PMID 27223472, 2016). "The chromatography analyses indicated an increase of all detected CS and HS disaccharide units in tumour tissue compared to normal mammary tissue, whereas the deletion of serglycin not significantly changed the overall CS and HS disaccharide content in the primary tumours." (PMID 27223472, 2016). "A lack of serglycin may affect both the recruitment process of these inflammatory cells to the tumor as well as the function of the cells once residing in the tumor tissue." (PMID 25978773, 2015). "To investigate how a systemic lack of serglycin affects different parameters important for tumor progression in an in vivo mouse-model system for spontaneous tumor development, we crossed female serglycin knockout mice with males from the transgenic RIP1-Tag2 strain." (PMID 25978773, 2015). "To assess whether lack of serglycin has any additional effect on the tumor vasculature we initially measured vessel density by staining for the endothelial marker CD31." (PMID 25978773, 2015). "However, SRGN's role in tumorigenesis and tumor progression of HCC has not been investigated." (PMID 40384866, 2025). "However, despite changed protein levels of some angiogenic and inflammatory mediators, the tumour progression, i. e. overall vascularization and tumour growth, was intact in the SG-/- mice suggesting that expression of serglycin is not essential for primary tumour growth." (PMID 27223472, 2016).
tumor (continued). "SRGN and TGFβ2 protein expression in TNBC tumor tissues was significantly higher than that in non-TNBC tumor tissues [Luminal A (P<0.001), Luminal B (P<0.05), and HER2 (P<0.01)]." (PMID 28692037, 2017). "Our results show that SRGN mRNA and protein expression levels were significantly higher in TNBC cell lines and tumor tissues than that in non-TNBC cells and tissues." (PMID 28692037, 2017). "In the present model investigation of the primary tumours indicated that cancer related inflammation and epithelial to mesenchymal transition (EMT) were affected in mice lacking serglycin." (PMID 27223472, 2016).